CDK2 (cyclin dependent kinase 2)
Diseases named in the same sentence as CDK2 in open-access papers (continued):
Sharing a sentence is not in itself a finding about the gene and the disease.
cancer (continued). "In various cancers, CDK2 has corresponding systematic significance with several clinical aspects (P < 0.05)." (PMID 34409029, 2021). "Cancer cell responsiveness to palbociclib is increased by inhibiting the PI3K signaling pathway through the suppression of post-mitotic CDK2." (PMID 34361615, 2021). "As m6A RNA methylation participates in the pathogenesis of multiple diseases including cancer, the potential roles of CDK2/4/6 in m6A RNA modification in human HCC require further investigations." (PMID 33579185, 2021). "For instance, circFOXO3, a circRNA downregulated in cancer cells, forms an RNA–protein complex with cyclin-dependent kinase 2 (CDK2) and p21, which disrupts the interaction of CDK2 with cyclin A and cyclin E, and subsequently blocks cell cycle progression." (PMID 33466455, 2021). "By UALCAN, Oncomine and R packages, we explored the expression levels, survival analyses of CDK2 in 33 cancers." (PMID 34409029, 2021). "Our data indicate ADAR1 as one of the main targets of METTL3 controlling cell proliferation and connecting, in a new molecular pathway, two key proteins (METTL3 and CDK2) important for cancer progression." (PMID 33509238, 2021). "In fact, specific targeting of oncogenic Cyclin E/CDK2 complex has been proposed as a promising therapy against cancer." (PMID 34901021, 2021). "Here, we used in silico analyses of multi-Omics data to map out the role of epigenetic and genetic alterations of STAT3/CDK2/4/6 in tumor immune infiltrations, immunotherapy response, and prognosis of cancer patients." (PMID 33668805, 2021). "Several studies reported TQ’s cell cycle arrest action through inhibition of cyclin D, cyclin E and cyclin-dependent kinase 2 (Cdk-2) in various cancers." (PMID 33540625, 2021). "But we explored detailed information of CDK2 in 33-cancer, a pan-cancer analysis was shown in our study." (PMID 34409029, 2021). "Through the Oncomine database, CDK2 expression was higher in 15 cancer tissues in comparison with normal tissues." (PMID 34409029, 2021). "While the RB1 gene is rarely altered in these cancers, the RB1 protein is disabled by cyclin E, CDK2 and/or CDK4/6 upregulation as well as by loss of the CDK inhibitors, p27 and p16INK4a, in essentially all MPNSTs." (PMID 34065204, 2021). "The target CDK2 is a vital protein kinase involved in cell cycle regulation induces arrest in G2 phase that has been effectively used as inhibitors to suppress cancer." (PMID 33921173, 2021). "In normal human fibroblasts and cancer cells, Pol κ is important for the tolerance of Cyclin E/CDK2-induced DNA replication stress, while Pol η confers tolerance to Myc-induced replication stress in cancer cells." (PMID 33961649, 2021). "Our results demonstrated that the expression of CDK2/4/6 was altered in various cancers and is associated with both shorter OS and DFS of the cancer patients." (PMID 33668805, 2021). "For instance, circ-Foxo3 can form a complex with p21 protein and cyclin-dependent kinases 2 (CDK2), inhibit CDK2 function, block the transformation from the G1 phase to S phase, thereby holding back the proliferation of cancer cells." (PMID 33777954, 2021). "FCL was demonstrated to induce G1-S arrest by suppressing the expression of Cyclin D/E and CDK2/4/6 in several human cancers." (PMID 34195076, 2021). "For example, in the C-T network, ICT, kaempferol and sitosterol target proteins associated with inflammation, cancer cell apoptosis and migration in the TME, such as COX2, IL-6, GSK3β, CDK2 and NOS3." (PMID 33460401, 2021). "New synthetic analogs of 2-thiouracil-5-sulphonamides were synthesized, screened for their anti-cancer effect against a panel of four cancer cell lines and in-vitro CDK2 inhibition activity." (PMID 34769385, 2021). "The Genomics of Drug Sensitivity in Cancer (GDSC) database was used to explore correlations between CDK2 expression and IC50 of anti-tumor drugs." (PMID 34409029, 2021).
cancer (continued). "A vast number of studies has been performed to discover and develop new selective CDK2 inhibitors for cancer therapy with minimal off-target toxicity." (PMID 33466812, 2021). "Pan-cancer analysis revealed that the expression, stage and survival of CDK2 in 33 cancers, which were statistically significant." (PMID 34409029, 2021). "Through different R packages, the expression of CDK2 was relatively higher in 17 cancers (P < 0.05)." (PMID 34409029, 2021). "To answer this question, we tracked single-cell proliferation in real time over 5 days using time-lapse imaging of a fluorescent biosensor for CDK2 activity coupled with EllipTrack29, our new cell-tracking pipeline optimized for hard-to-track cancer cells." (PMID 33741929, 2021). "Conversely, studies using nobiletin in cancer cells (U87, Hs683) showed a decrease in CDK2 expression." (PMID 34083641, 2021). "The activating phosphorylation on threonine 160 (T160) of cyclin dependent kinase 2 (Cdk2) was significantly reduced when methionine-dependent cancer cells were cultured in homocysteine medium." (PMID 32276408, 2020). "Regarding the downstream effector of miR-1179, CDK2, several studies have reported that CDK2 is the downstream effector of miRNAs in various cancers." (PMID 32699532, 2020). "CDK2 was noted in another research to form a complex substance with circ-Foxo3; this substance was abnormally expressed in cancer tissues in terms of participating in cell cycle regulation." (PMID 32699532, 2020). "Subsequently, by acting on these key regulators, silibinin blocks cell cycle progression which is reinforced by a cytoplasmic sequestration of cyclin D1 and Cdk2 contributing to this G1 arrest and finally the cancer cell proliferation." (PMID 32344919, 2020). "Taken together, these results suggest that inhibition of CDK2 can prevent the formation of the cyclin E-CDK2 complex, thereby inhibiting the proliferation of cyclin E-overexpressed cancer cells." (PMID 33260316, 2020). "Accumulated evidence demonstrated that overexpression of CDK2 leads to abnormal cell-cycle regulation, which is directly related to hyperproliferation in cancer cells." (PMID 32093300, 2020). "This has prompted the suggestion that the predominance of Cdk6–Cyclin D-p27 trimers depletes p27 from the pools of Cdk2 to elevate Cdk2 activities and confer palbociclib resistance in cancers in which Cdk6 expression is elevated." (PMID 33052073, 2020). "CDK2 was also up-regulated in many cancers as a cell cycle-dependent kinase that contributed to cell cycle progression and DNA damage responses." (PMID 32699532, 2020). "The continuous activation of the NF-κB pathway can increase antiapoptotic gene Bcl-2 expression, upregulate expression of proliferation-related proteins CDK1 and CDK2, and promote cell cycle, thus promoting cancer cell proliferation." (PMID 32337232, 2020). "Specific degradation of p27 from cyclin E/A-CDK2 complexes would be a cunning oncogenic mechanism, enabling cancer cells to hyperactivate CDK2, while simultaneously retaining high CDK4 activity." (PMID 33166394, 2020). "Nevertheless, numerous evidence indicates that CDK2 is critical to the abnormal growth processes of cancer cells." (PMID 33198081, 2020). "Apart from the fact that a previous study uncovered that CDK2-related signaling pathways conferred complicated roles in several forms of cancers, a few studies have investigated the tumor-promoting role of CDK2 in CC." (PMID 32699532, 2020). "Fadraciclib preclinical pharmacology data support its therapeutic potential in CDK9- or CDK2-dependent cancers and as a rational combination with BCL2 inhibitors in hematological malignancies." (PMID 32645016, 2020).
cancer (continued). "Apart from observing that circ_0084927 abolished miR-1179’s inhibitory effects on cell proliferation and adhesion, it was found that CDK2 was up-regulated in CC tissues and was instrumental in cancer promotion." (PMID 32699532, 2020). "miR-16 was likely to suppress cancer growth by regulating the expression of genes such as CDK1 and CDK2, which are associated with cell cycle control and cellular proliferation." (PMID 32774515, 2020). "The results shown are consistent with the principal anti-cancer effects of the drug being mediated by inhibition of CDK2 and CDK9, for which IC50 values are 4.5 and 26 nM respectively." (PMID 32645016, 2020). "Similar to the results in various cancer cells, our result demonstrated that genistein decreased the expression of cyclin A and B1, whereas the expression of CdK2 and Cdc2 remained at the control level." (PMID 31438633, 2019). "The compounds most transcriptionally similar to chronic GA treatment belonged to the Topoisomerase II and CDK2 inhibitors drug class, agents widely used for human cancer treatment that prevent unregulated cancer cell proliferation leading to apoptosis." (PMID 30862866, 2019). "Here, we report that activation of the MET/FAK signalling axis leads to CDK4/6-independent CDK2 activation, and constitutes a broadly applicable druggable means to improve the response of cancers to CDK4/6-targeted therapies." (PMID 31296956, 2019). "Widespread recognition exists that CDK2 activation is associated with acquired resistance of cancer cells to CDK4/6-targeting cancer therapeutics and also that CDK2 supports CDK4/6-independent proliferation during organismal development." (PMID 31296956, 2019). "The VEGF/NRP-1 pathway is involved in the proliferation of cancer cells by activating Akt, leading to sequential downregulation of p27, which binds to CDK2 and suppresses the activity of CDK2/cyclin E complex." (PMID 31572065, 2019). "During the cell cycle of cancer cells during cancer progression, Slug is also phosphorylated by cyclin E/ CDK2, which promotes its proteasomal degradation at the G1/S phase transition." (PMID 31275381, 2019). "We have shown that MF and MF-related compounds block growth of cancer cells inhibiting the activity of cyclin-dependent kinase Cdk2 as a consequence of p21cip1 upregulation." (PMID 31014286, 2019). "Increased expression of cyclin-dependent kinase 2 (CDK2) was also observed in this type of cancer, suggesting its correlation with the Akt/mTOR signaling." (PMID 31370278, 2019). "Cyclin E is overexpressed in cancer, suggesting that cyclin E/CDK2 deregulation contributes to tumorigenesis." (PMID 31336900, 2019). "The high expression of cyclin E1 in ~26% of BLBC also raises the possibility of CDK2 inhibition to target these cancers." (PMID 30720718, 2019). "High expression levels of CDK2, SKP2 and CDC25A are detected in several types of cancer, BC included, and implicated in the promotion of cancer cell proliferation." (PMID 31107884, 2019). "CDK2 gene is commonly excessive activation in human cancers, and dysfunction of CDK2 can lead to uncontrolled cell growth." (PMID 32038722, 2019). "The dysregulation of CDK2 is observed in the breast and other cancer, thereby making it a potential drug target for anticancer therapy." (PMID 31847444, 2019). "The G1/S restriction point is side-stepped in these cancers either through depletion of RB or elevation of E2F/CDK2 activity." (PMID 30720718, 2019). "The catalytic activity of CDK2-CyclinE complexes is hyperactivated in several cancers by Cyclin E amplification, or a loss-of-function mutation of FBXW7, a ubiquitin ligase for Cyclin E degradation, although CDK2 mutations are rare in human cancers." (PMID 29540837, 2018).
cancer (continued). "To further validate our findings, we probed the correlation of MITF and CDK2 in the publicly available Cancer Cell Line Encyclopedia (CCLE) containing 935 cell lines." (PMID 29507054, 2018). "PHA-793887 is a CDK2-specific inhibitor that exhibits favorable efficacy against cancer xenografts and disrupts DSB end resection after radiation." (PMID 30135856, 2018). "Particularly, the cell cycle and mitotic regulatory genes expression including: CDK2, CDK2AP2, ACTR3, and chromosome structure associated genes like SMC4, INCENP and GNL3L are changed in treated cancer cells." (PMID 30202240, 2018). "As CDK2/5 have been known to drive proliferation of cancer cells, we investigated the effect of 20-223 on cell growth in a larger panel of CRC cell lines." (PMID 29435174, 2018). "CDK2 is considered a significant therapeutic target for cancer therapy because it plays a vital role in regulating the cell cycle." (PMID 30423939, 2018). "Supplemental mevalonate increased the proliferation of cancer cells by upregulating cyclin-dependent kinase 2 (CDK2) activity and accelerating entry of cells into the S phase of cell division cycle." (PMID 30662405, 2018). "To investigate how WTAP regulated the cell proliferation of RCC cancer cells, we used western blot to investigate the expression change of cell cycle related protein CDK2, CDK4 and CDK6 by the knockdown or overexpression of WTAP." (PMID 29482572, 2018). "To date, numerous CDK2 inhibitors have been designed and developed as potential cancer therapeutic agents such as RGB-286638, ZK-304709, P1446A-05, AZD5438, and AG-024322." (PMID 30423939, 2018). "Taken together, these results suggest that cyclin E has kinase-independent roles and that there are subtle differences by which cyclin E and its CDK–partner CDK2 are exploited in cancer progression." (PMID 30185601, 2018). "Previous studies have shown that flavonoids can inhibit CDK activity in human cancer cells in the nanomolar concentration range and structural studies show that CDK2 can form complexes with flavonoids." (PMID 29253187, 2018). "IHC and western blotting were performed to detect the protein expression characteristics of β-catenin and CDK2 in the BCa and para-carcinoma tissues." (PMID 30237499, 2018). "Consistent with these important functions are the involvement of CDK2 kinase complexes in diseases, including cancer." (PMID 28056778, 2017). "In both non-cancer and cancer granulosa cells, leptin acts as a cyclinD/cdk4, cyclin A/cdk2 and E2F inhibitor." (PMID 28861689, 2017). "What’s more, targeting CDK2 has been reported to inhibit invasion, migration together with outgrowth in various cancers." (PMID 29088865, 2017). "It regulates genes associated with cell proliferation (cyclin D, cyclin E, Cdk2, E2F-1, c-Myc), metastasis (VEGF), and apoptosis (survivin, XIPA), all of which contribute to the hallmarks of cancer." (PMID 28099934, 2017). "Cancer patients with high CCNE1 expression levels have shown increased sensitivity to CDK2 inhibitors SNS-032." (PMID 28178664, 2017). "This is surprising because Cyclin E is overexpressed in several cancers and Cyclin E/CDK2 activity is a major driver of cell-cycle progression." (PMID 28892491, 2017). "Complex of cyclin A and cdk2 is required to progress through the S phase and plays important role in G1 cell cycle arrest of cancer cells." (PMID 28289384, 2017). "It would be interesting, and possibly of clinical relevance, to see if different growth conditions can also change the dependency of individual cancer cell lines on Cdk2 for their arrest in response to replication poisons." (PMID 29044141, 2017).
cancer (continued). "Using Western blot, we found that cell-cycle associated factors were upregulated in the group A antigen-expressing 231-A6 cancer cells, including Cyclin D, Cyclin E, CDK2, CDK6, E2F, and ATM." (PMID 28122343, 2017). "Through their binding to cdk2 and cdk4, p21 and p27 have been reported to induce blockade of G1/S transitions of cell cycle and then premature senescence in cancer cells." (PMID 28289384, 2017). "Our research laboratory and the laboratory of Bruno Amati demonstrated a direct connection between MYC and CDK2 in modulating cellular senescence in normal cells and cancer cells." (PMID 28665315, 2017). "Dinaciclib, a potent CDK2 inhibitor (as well as CDK1, CDK5, and CDK9 inhibitor) that is currently in clinical trials for several cancers, was used to target the cyclin E/CDK2 pathway." (PMID 28107181, 2017). "This evidence is in agreement with findings reported for other tumours, which demonstrated that downregulation or inhibition of CDK2 prevents cancer cells proliferation." (PMID 27898692, 2016). "The results displayed—for the first time—that prostaglandin E1 and NDGA are promising CDK2 allosteric inhibitors, which also can be used as leading compounds for designing novel CDK2 allosteric inhibitors and anti-cancer drugs." (PMID 27657032, 2016). "Nevertheless, inhibition by small molecules inhibiting Cdk5 and additionally Cdk1, Cdk2, Cdk7, and Cdk9 have shown promising effects in cancer/angiogenesis." (PMID 26755662, 2016). "Given the CDK2 allosteric inhibitors with anti-cancer effect, the first known extrinsic allosteric inhibitor, ANS, was acted as a positive control in the MTT assay." (PMID 27657032, 2016). "In particular, the transition of cell cycle from the G1/G0 to the S phase is regulated by CDK2, and its excess activity is correlated with the deregulated cell proliferation rates in cancers." (PMID 27385212, 2016). "Since CDK2 is associated with CIS resistance, it is an important candidate target for cancer therapy." (PMID 27514524, 2016). "RT-PCR and Western blot assays detected the expression of known targets of miR-372 in other malignant tumors and found Cyclin A1 and Cyclin-dependent Kinase 2 (CDK2) was downregulated by miR-372." (PMID 26673619, 2016). "The results of apoptosis assays and cell cycle analysis demonstrated that compound 9a obviously inhibits the proliferation of MCF-7 cancer cells by inducing apoptosis and arresting the cell cycle at G1 phase via inhibition of CDK2 and CDK4." (PMID 26901182, 2016). "It has been reported that the cell cycle regulatory protein expression of cyclin A, cyclin E, cyclin D, Cdk4, Cdk6 and Cdk2 were inhibited by the activation of p21 in human cancer cells." (PMID 27007366, 2016). "CDK2 allosteric inhibitors have the effect of anti-cancer and the known CDK2 inhibitor, ANS, was used as a positive control." (PMID 27657032, 2016). "The growth inhibitory effect of the most promising compounds and ANS was determined on human HepG2 cell lines which suggested the screened compounds should interact with the allosteric pocket of CDK2 to play the anti-cancer effect." (PMID 27657032, 2016). "Progression from G1 to S phase is regulated by a number of the cyclin family members, in particular cyclin A and cyclin E. Meanwhile, CDK2 is pivotal for the G1-S phase transition and mitosis of the cancer cell cycle." (PMID 27223122, 2016). "On the other hand, carcinomas control this signaling cascade by using the opposite way (CDK2 and CCNE1)." (PMID 27802291, 2016). "CDK2 expression gradually increases from normal through hyperplasia to carcinoma, indicating its potential importance in both early and late carcinogenesis in EC." (PMID 26673619, 2016). "The new identified targets for cancer therapy in future using luteolin can be CDK2, CDK6, HGFR, MAPK14, FGF." (PMID 26385094, 2015). "From the medicinal perspective, CDK2 has long been a classical and important target for cancer therapy." (PMID 26147897, 2015).